METTL23 (methyltransferase 23, arginine)
Description:
Histone methyltransferase that dimethylates histone H3 at 'Arg-17', forming asymmetric dimethylarginine (H3R17me2a), leading to activate transcription via chromatin remodeling (By similarity). Maternal factor involved in epigenetic chromatin reprogramming of the paternal genome in the zygote: mediates H3R17me2a, promoting histone H3.3 incorporation in the male pronucleus, leading to TET3 recruitment and subsequent DNA demethylation (By similarity).
Synonyms: C17orf95; LOC124512; MRT44
Tractability: PROTAC: ubiquitination databases record sites on it.
Gene: Protein-coding gene on chromosome 17 (76,725,981 to 76,733,936, forward strand). Ensembl gene ENSG00000181038.
Subcellular location: Nucleus; Cytoplasm
Subcellular location (Human Protein Atlas): Vesicles
Pathways (Reactome):
Developmental Biology: Chromatin modifications during the maternal to zygotic transition (MZT); Replacement of protamines by nucleosomes in the male pronucleus
Gene Ontology:
Molecular function: DNA-binding transcription factor binding; heat shock protein binding; protein binding; histone H3R17 methyltransferase activity; protein-arginine omega-N asymmetric methyltransferase activity
Biological process: cognition; positive regulation of transcription by RNA polymerase II; epigenetic programing of male pronucleus; epigenetic programming in the zygotic pronuclei; epigenetic regulation of gene expression; regulation of gene expression
Cellular component: cytoplasm; nucleus; protein-containing complex; female pronucleus; male pronucleus
Genetic constraint (gnomAD): Loss-of-function variants: 24 observed, 18.88 expected, observed/expected ratio (o/e) 1.27, 90% interval 0.92 to 1.76. The upper end of that interval is the gene's LOEUF score, 1.76, which puts it in group 6 of 6, group 1 being the genes least tolerant of losing a copy. Missense variants: 275 observed, 213.85 expected, observed/expected ratio (o/e) 1.29, 90% interval 1.16 to 1.42. Synonymous variants: 97 observed, 75.19 expected, observed/expected ratio (o/e) 1.29, 90% interval 1.09 to 1.53.
Gene-disease validity (ClinGen):
ClinGen rates the evidence that METTL23 causes each of these diseases.
intellectual disability (autosomal recessive): Definitive.
Homologues: Orthologues: chimpanzee METTL23 (99% identical), macaque METTL23 (98% identical), dog METTL23 (92% identical), mouse Mettl23 (89% identical), pig METTL23 (89% identical), rabbit METTL23 (83% identical), rat Mettl23 (74% identical), zebrafish mettl23 (62% identical), tropical clawed frog mettl23 (58% identical), zebrafish METTL23 (53% identical), Drosophila melanogaster CG5013 (44% identical). Paralogues in human: METTL21C (29% identical), METTL21A (26% identical), METTL21EP (26% identical), EEF1AKMT3 (23% identical), VCPKMT (23% identical).
Diseases named in the same sentence as METTL23 in open-access papers:
METTL23 is named in the same sentence as 14 diseases in open-access papers, as found by Europe PMC text mining. Sharing a sentence is not in itself a finding about the gene and the disease. The quoted sentences say what the papers report.
Intellectual disability (4 papers, 2015 to 2023). "METTL23 is known to function as a regulator in the transcriptional pathway for human cognition and has been associated with mental retardation and intellectual disability." (PMID 33849068, 2021). "A similar approach was used to identify the causal gene in other UAE families, such as METTL23 in a large inbred UAE family of Yemeni origin with intellectual disability and SRD5A3 in another UAE family of Baluchi origin with a new type of glycosylation disorder." (PMID 37214420, 2023). "Human METTL23, a MT Family 16 member without a yet described target, is associated with intellectual disability and interacts with the transcription factor GABPA." (PMID 26544960, 2015).
normal tension glaucoma (4 papers, 2023 to 2024). "It reported a splicing mutation in the methyltransferase-like 23 (METTL23) gene, which encodes a histone arginine methyltransferase, in a Japanese family spanning three generations of patients with normal tension glaucoma." (PMID 37725658, 2024). "OPTN, TBK1, and METTL23 are responsible for early onset normal-tension glaucoma with autosomal dominant inheritance, characterized by significant optic atrophy despite normal IOP." (PMID 38671671, 2024). "METTL23, a histone arginine methyltransferase expressed in RGCs, which catalyzes dimethylation of histone H3R17 in the retina, when mutated (c.A23G variant) is involved in normal tension glaucoma development." (PMID 38474069, 2024).
glaucoma (3 papers, 2022 to 2024). Increased pressure in the eyeball due to obstruction of the outflow of aqueous humor. "Taken together, we reason that the glaucoma-causing METTL23 mutation evokes loss of function because its spliced mRNAs lack at least 1 functional motif, or as a result of the abolishment of translation." (PMID 36099048, 2022). "Moreover, many of the studies on the METTL23 gene have been about human intelligence, and there were also studies showing that the METTL23 gene was associated with glaucoma in humans." (PMID 39202421, 2024). "Mettl23–knock-in (Mettl23+/G and Mettl23G/G) and -knockout (Mettl23+/– and Mettl23–/–) mice developed a glaucoma phenotype without elevated IOP." (PMID 36099048, 2022). "Notably, the affected individuals of the NTG family also developed glaucoma with normal IOP, suggesting a role for Mettl23-KI and -KO murine models in studying certain aspects of human glaucoma." (PMID 36099048, 2022).
mental disorder (1 paper, 2022). A disease that has its basis in the disruption of mental process. "Eight genes are implicated in viral (SEC14L1, JMJD6, SRSF2, TMPRSS2, MX1, MX2) or bacterial (COL8A1, SPIRE1) infections, seven genes (MFSD11, METTL23, CTTNBP2, BACE2, IMPA2, MPPE1 and GNAL) are involved in mental disorders and one gene (MGAT5B) is related to the Golgi complex." (PMID 35581286, 2022).
ovarian carcinoma (1 paper, 2023). A malignant neoplasm originating from the surface ovarian epithelium. "METTL23 has been validated as a prognostic marker in prostate cancer, and the coactivation properties of WDR77 on the androgen receptor have been linked to ovarian cancer." (PMID 38132437, 2023).
viral infection (1 paper, 2026). "Furthermore, we identified METTL23 as a nuclear interactor of JMJD6 upon viral infection, revealing a cooperative role between these proteins in facilitating immune evasion." (PMID 42053297, 2026).
genetic diseases (1 paper, 2025). "Further studies are needed to investigate the possibility that CARM1 and METTL23 are involved in genetic diseases caused by lack of XPF activity and to approach anticancer drug resistance from the perspective of CARM1 and METTL23." (PMID 40304182, 2025).
neurological disorders (1 paper, 2022). "Indeed, identified genes are implicated in viral (SEC14L1, JMJD6, SRSF2, TMPRSS2, MX1, MX2) bacterial (COL8A1, SPIRE1), and neurological disorders (MFSD11, METTL23, CTTNBP2, BACE2, IMPA2, MPPE1 and GNAL), or in the functions of the Golgi complex (MGAT5B), organelle where viral envelope is occurred." (PMID 35581286, 2022).
METTL23 also shares sentences with these, for which no sentence is quoted: glycosylation disorder (1 paper); multiple sclerosis (1); optic atrophy (1); osteoporosis (1); prostate carcinoma (1); sarcopenia (1).